TNF (tumor necrosis factor)
Diseases named in the same sentence as TNF in open-access papers (continued):
Sharing a sentence is not in itself a finding about the gene and the disease.
autism (continued). "Although TNF-alpha was related to autism symptoms in previous studies, in our study, the lack of significance between the levels of TNF-alpha may be due to sample size limitation, slight differences regarding sex distributions, and possibly biological variability." (PMID 39337983, 2024). "Additionally, the levels of IL-6 and IL-17, but not TNF-α and IL-1β, were consistently higher in the unstimulated neutrophils, monocytes, and CD4+ T cells in autism subjects, as opposed to the controls." (PMID 36268027, 2022).
hepatitis C (85 papers, 2008 to 2025). "Hepatitis C is an inflammatory disease associated with elevated expression levels of IL(interleukin)-6 and TNF(tumor necrosis factor)-α." (PMID 36901973, 2023). "TNF-α A/G and A/A genotypes have been significantly associated with susceptibility to hepatitis C infection, and a significant association between TNF-α −308 G/G genotype and HCV infection was seen in patients compared with healthy individuals." (PMID 34572300, 2021). "The KEGG pathway showed enrichments in pathways related to Hepatitis C (mmu05160), IL-17 signaling (mmu04657), Toll-like receptor signaling (mmu04620), TNF signaling (mmu04668), Glycosaminoglycan degradation (mmu00531), and cAMP signaling (mmu04024)." (PMID 40243536, 2025). "The upregulated dif-mRNAs primarily enriched in Influenza A, TNF signaling pathway, cytosolic DNA-sensing pathway, cytokine-cytokine receptor interaction, Measles, and Hepatitis C." (PMID 36532076, 2022). "Hepatitis C is an inflammatory disease associated with elevated expression levels of IL-6 and TNF-α (tumor necrosis factor-α)." (PMID 35887291, 2022). "The target genes of circRNAs were highly enriched in the TNF signaling pathway and Hepatitis C. However, the target genes of miRNAs were only enriched in the TGF-beta signaling pathway." (PMID 33912180, 2021). "The enriched KEGG pathways of GSEA showed that cardiac muscle contraction, dilated cardiomyopathy, hepatitis C, herpes simplex virus 1 infection and TNF signaling pathway are significantly enriched in DCM." (PMID 34970603, 2021). "The most enriched pathways of the DE circRNAs involved included lysine degradation, the TNF signaling pathway, the B cell receptor signaling pathway, and hepatitis C." (PMID 33912180, 2021). "Utilizing a prospective study design, we recruited 30 patients (mean 48.0 ± 10.5 years, 21 male) initiating IFN-α treatment for Hepatitis-C and 30 (mean 50.4 ± 15.7 years, 10 male) anti-TNF therapy for inflammatory arthritis." (PMID 32457424, 2021). "Hepatitis B, TNF signaling pathways, NF-kappa B signaling, cytokine-cytokine receptor interaction, and hepatitis C pathways are related to inflammatory reactions." (PMID 33123211, 2020). "The total RNAs obtained from δ-tocotrienol treated hepatitis C patients showed significant decrease in expression of pro-inflammatory cytokines such as TNF-α (47%; P < 0.001), VCAM-1 (22%; P < 0.01)." (PMID 29606130, 2018). "The total RNAs obtained from plasmas of δ-tocotrienol treated hepatitis C patients showed significant decreases in the expression of TNF-α (47%) and VCAM-1 (22%) pro-inflammatory cytokines." (PMID 29606130, 2018). "For TNF-α, the findings from the limited number of previous studies conducted are consistent with ours; for example, in patients with hepatitis C, TNF-α correlated with scores of neuroticism after therapy." (PMID 30524320, 2018). "Recent studies of hepatitis C infection directly implicate the sustained upregulation of the cFLAR gene product in preventing TNF-α-mediated apoptosis and contributing to disease initiation by the virus core protein." (PMID 19014542, 2008). "Additionally, some research highlighted that patients with chronic hepatitis B had a Th1 response with higher levels of IFN-γ, TNF-α, and IL-2, when compared to patients with hepatitis C and healthy individuals." (PMID 40559733, 2025). "But the use of TNF-α inhibitors and other biological agents in patients with hepatitis C virus infection may activate viral replication and aggravate the condition of hepatitis C patients." (PMID 34215260, 2021). "Corilagin has also been reported to cause the release of TNF-α inhibitor in inflammation, decrease the secretion of the transforming growth factor beta 1 (TGF-β1) in a dose dependent manner, and inhibit hepatitis C viral replication in vitro." (PMID 30609707, 2019).
hepatitis C (continued). "In addition to that, effect of δ-tocotrienol on expression of proteasome subunits (X, Y, Z, LMP7, LMP2, LMP10), ICAM-1, VCAM-1, and TNF-α using total RNAs derived from plasmas of hepatitis C patients was investigated." (PMID 29606130, 2018). "Similarly, these receptors were to be involved in TNF-α production in studies on hepatitis C and L. donovani." (PMID 25706930, 2015). "In patients with chronic hepatitis B and hepatitis C, serum lipid levels have been reported to be correlated with specific cytokines that may have antiviral activity, including tumor necrosis factor-alpha and interleukin-6." (PMID 23193392, 2012). "Furthermore, CD163+ monocytes can secrete both pro- and anti-inflammatory cytokines such as TNF-α and IL-4 during Leishmania and hepatitis C infection, which might interfere in instructing T cells and inhibit the killing of intracellular pathogens." (PMID 31779590, 2019). "Moreover, results of plasma total mRNAs after δ-tocotrienol feeding to hepatitis C patients revealed significant inhibition in the expression of pro-inflammatory cytokines (TNF-α, VCAM1, proteasome subunits) and induction in the expression of ICAM1 and IFN-γ after post-treatment." (PMID 30031388, 2018). "KEGG pathway analysis showed that DEGs play a key role in hepatitis C/B, RIG-I-like receptor signaling pathway, and TNF signaling pathway." (PMID 36915717, 2023). "A similar increase in TNF-α, along with a marked elevation in total and activated B cells and IL-8 was reported in human heroin users with HIV and hepatitis C (n = 19) compared to controls (n = 19)." (PMID 37112606, 2023). "A preliminary pilot study was carried out on the effect of δ-tocotrienol feeding in hepatitis C patients on six protease subunits (X, Y, Z, LPM7, LMP2 and LMP10), ICAM-1, VCAM-1, and TNF-α using total blood mRNA of these patients." (PMID 29606130, 2018). "Unlike the pathways modulated similarly by the two viruses, the nonlethal CSFV vPdR-36U upregulated specifically the TNF signaling pathway, the platelet activation pathway, the hepatitis C pathway, and the protein digestion and absorption pathway." (PMID 40006915, 2025). "Furthermore, previous studies have revealed that IL-26 upregulates tumor necrosis factor (TNF)-related apoptosis-inducing ligand (TRAIL) expression in human NK cells, which induces the elimination of hepatitis C-infected hepatocytes." (PMID 29698503, 2018). "Diverse pro-inflammatory cytokines, such as IFN-α, TNF-α, IL-1β, or IFN-γ induce sphingolipid metabolizing enzymes and especially IFN-α has already been shown to effect a decrease, for example, in HDL cholesterol in hepatitis C patients treated with IFN-α." (PMID 27857690, 2016).
allergic asthma (84 papers, 2012 to 2026). A asthma with a basis in a pathological type I hypersensitivity reaction. "Although TNF-α levels remained unchanged, Th2 cytokines associated with allergic asthma (i.e. IL-4, IL-5, and IL-13) were substantially reduced in BALF following ITIH4 administration (p < 0.05)." (PMID 40410722, 2025). "TNF-α is an important proinflammatory cytokine and has been implicated in the mechanisms of several inflammatory diseases, such as allergic asthma, inflammatory bowel disease, and rheumatoid arthritis." (PMID 25658739, 2015). "A major hallmark of allergic asthma is the local overproduction by alveolar macrophages, of injurious inflammatory response activators, including NO or TNF-α." (PMID 24098413, 2013). "During a cytokine storm, immune and non-immune cells would release a large number of pro-inflammatory cytokines, including IL-6, tumor necrosis factor-α (TNF-α), and chemokines, which would cause substantial damage to the host immune response and further induce various ADs such as allergic asthma." (PMID 38263182, 2024). "AHR considered as a hallmark of allergic asthma, may also be evoked by neutrophilia and increases in pro-inflammatory cytokines such as TNF-α and IL-1β." (PMID 37464447, 2023). "Dietary PSO probably attenuates allergic asthma inflammation through suppressing the secretion of pro-inflammatory cytokine IL-1β, IL-6, and tumor necrosis factor (TNF)-α in the airways, lungs, and spleen of mice with allergic airway inflammation." (PMID 39598647, 2024). "Patients with allergic asthma have elevated serum levels of tumor necrosis factor alpha (TNF-α), a pro-inflammatory cytokine, due to increased expression by mucosal mast cells." (PMID 40474934, 2024). "Based on this, we investigated the efficacy and mechanism of SXCF in allergic asthma by combining inflammatory factors such as TNF-α, IL-4, IL-10, IFN-γ, serological indicators, behavioural results, and pathological results." (PMID 36937885, 2023). "On the other hand, in a mouse model of allergic asthma, HDM was reported to cause airway epithelial cell necroptosis, a process proposed to be mediated by the induction of death receptor ligands such as TNF and TRAIL." (PMID 37234176, 2023). "In the present study, a widely used allergic asthma mouse model has been established, in which the levels of IgE, TNF-α, and IL-5 are successfully upregulated by OVA compared with the NC control." (PMID 35371026, 2022). "Kaempferol suppresses eosinophil infiltration and airway inflammation in airway epithelial cells and in mice with allergic asthma through inhibition of TNF-α." (PMID 34557554, 2021). "In allergic asthma, it is produced by both immune and structural cells, and its upregulation is induced by pro-asthmatic cytokines such as TNF and IL-1β." (PMID 35387000, 2021). "In allergic asthma, pentraxin-3 is produced by immune and structural cells and is up-regulated by pro-asthmatic cytokines such as TNFα and IL-1β." (PMID 35387000, 2021). "Morin treatment downregulated the expression of BLT2, NF-κB, and Th2-cytokine (IL-1β, IL-4, IL-6, IL-13, and TNF-α) in the lungs of an allergic asthma rat model." (PMID 33917985, 2021). "In this study, we investigated anti-inflammatory and anti-oxidant effects of the methanolic extract of L. obtusiloba leaves (LOL) in an ovalbumin (OVA)-challenged allergic asthma model and tumor necrosis factor (TNF)-α-stimulated NCI-H292 cell." (PMID 32605045, 2020). "This is the first study to demonstrate that treatment with LOL effectively attenuates airway inflammation, mucus hypersecretion, and ROS-mediated oxidative stress in the OVA-challenged allergic asthma model and TNF-α-stimulated NCI-H292 cell." (PMID 32605045, 2020). "It shows ability to inhibit the production of inflammatory mediators, such as IL-1β, IL-6, and TNF-α in macrophages and in mice with allergic asthma." (PMID 30809149, 2019).
allergic asthma (continued). "In contrast, Th1-derived cytokines including interferon (IFN)-γ, IL-2, IL-3, and tumor necrosis factor (TNF)-α protected against allergic asthma." (PMID 31024302, 2019). "NEt-4IB also reduced the numbers of CD4+ and CD8+ T cells, TNF-α levels, and nuclear factor-κB (NF-κB) expression in lung tissue in a murine model of allergic asthma." (PMID 30606200, 2019). "Increased levels of TNF-α were confirmed in bronchoalveolar lavage in the same DNFB-induced model of non-allergic asthma." (PMID 31614422, 2019). "It is well-documented that tumor necrosis factor alpha (TNFα), a pro-inflammatory cytokine, plays a significant role in the pathogenesis of chronic airway inflammatory diseases such as allergic asthma." (PMID 28659824, 2017). "Tumor necrosis factor alpha (TNFα), a pro-inflammatory cytokine, plays a significant role in the pathogenesis of allergic asthma." (PMID 28659824, 2017). "It is interesting to notice that the TLR-induced increase of AHR in our model was dampened when the mice were treated with infliximab suggesting a pivot role for TNFα in microbial induced exacerbation of allergic asthma." (PMID 26494305, 2015). "Previously, we proposed that TNF-α plays a key role in the allergic asthma model and alveolar macrophages can produce large amounts of TNF-α in the lung environment." (PMID 25658739, 2015). "The airway stabilizing effect of infliximab indicates the possible future use of TNFα blockade in treatment of microbial induced exacerbations of allergic asthma." (PMID 26494305, 2015). "TNFα is elevated in allergic asthma and in mouse models of allergic airway disease, wherein it initiates and amplifies pulmonary inflammatory responses." (PMID 25628603, 2014). "The fact that the alveolar macrophage mediated TNF-α production is crucial for the development of allergic asthma like features was supported by results from alveolar macrophage-depletion using Cl2MDP-containing liposomes." (PMID 23094102, 2012). "Upon intranasal administration of GCE into mice, allergic asthma-like features developed as a result of alveolar macrophage activation and TNF-α production in the lung tissue." (PMID 23094102, 2012). "Our results are consistent with the previous reports showing that alveolar macrophages are a major source of TNF-α in an allergic asthma model." (PMID 23094102, 2012). "Interestingly, IL-5 levels were consistently elevated in BT patients with allergic asthma (AA), suggesting persistent eosinophilic inflammation despite biological therapy, more likely unaffected by TNF-α or IL-17 blockade." (PMID 40364125, 2025). "KEGG pathways are linked to these targets, highlighting key pathways that could be therapeutically relevant in the treatment of allergic asthma (e.g., P13K-Akt signaling pathway, Th17 cell differentiation, TNF signaling pathway, and others." (PMID 39598467, 2024). "Pro-inflammatory factors such as IL-5, IL-13, TNF-α, and IL-6 play a leading role in the pathogenesis of allergic asthma, including the growth of eosinophils, the isotypic transition of B cells to IgE production, chemotaxis of neutrophils, and bronchial contraction." (PMID 39408735, 2024). "In humans, it is acknowledged that TNF-α plays an important role in allergic inflammation of the bronchus, with increased levels of expression being reported in the serum of patients with allergic asthma in acute attack, compared to healthy individuals or asthmatics in clinical remission." (PMID 31694631, 2019). "More recent is the notion that exacerbation of allergic asthma is also supported by lung neutrophil accumulation, increased production of acute phase proteins, such as the proinflammatory cytokines tumor necrosis factor-α (TNF-α) and IL-1β, and activation of nuclear factor-κB (NF-κB)." (PMID 31805682, 2019). "Additionally, TNF-α impairs the regulatory activity of natural Treg cells via the TNF-α receptor 2 (TNFR2) signaling pathway to down-modulate Foxp3 expression in allergic asthma." (PMID 27553600, 2016).
allergic asthma (continued). "Similarly, kaempferol abrogated the increase in Th2 cytokines and tumor necrosis factor-α levels through inhibiting the Akt activation in a mouse model of allergic asthma." (PMID 26694364, 2015). "Moreover, although TNFα is elevated in allergic asthma, the expression of IFNs is usually impaired, and the TNFα plus IFNγ-induced PANoptosis may be limited in normal allergic asthma." (PMID 37895022, 2023). "Furthermore, a recent study revealed that the inhibition of IL-6 and TNF-α could assist in the prevention of allergic asthma in a mouse model." (PMID 36501052, 2022). "Hence, further studies needs to outline whether it might be a future for specific anti-TNFα trials focusing on exacerbations of allergic asthma." (PMID 26494305, 2015). "Especially in neuroinflammation, studies have reported a reduction in the production of cytokines, such as IL-1β, IL-6, TNF-α, IL-12, and IL-17, and chemokines, such as IFN-Ɣ, MCP-1, MIP-1a, and MIP-1b in allergic asthma." (PMID 40243683, 2025). "In the BAL of patients with non-allergic asthma, we measured decreased concentrations of IL-4, IL-8, IL-13, IFN-γ, C4a, C5a, and MCP-1 and increased concentrations of IL-6, IL-12p70, TNF-α, and C3a." (PMID 40725075, 2025). "The role of IL-4, IL-5, IL-6, IL-33, TNF-α and IFN-γ in the pathogenesis of allergic asthma is well documented has been elaborately explicated elsewhere." (PMID 38807596, 2024). "With the additional control of lung IL-1β, IL-6, and TNF-α levels after OVA inhalation exposure, trifuhalol A has strong potential to be further evaluated as a therapeutic candidate for allergic asthma." (PMID 37998734, 2023). "integerrima reportedly subdued the expressions of inflammatory molecules, TNF-α, IL-4, and IL-5 in the mouse model of ovalbumin (OVA) induced allergic asthma, thereby alleviating pulmonary edema." (PMID 36386162, 2022). "Inflammatory cytokine secretion, such as IL-6 and TNF-α, is commonly regarded as an important indicator that reflects the severity of BMMC activation and OVA-induced allergic asthma." (PMID 34421593, 2021). "Further, BHT down-regulated expression levels of pro-inflammatory cytokines, such as TNF-α, IL-1β, IL-6, IL-8 and IL-17A indicating that BHT has an effect on declining pro-inflammatory response for allergic asthma." (PMID 32397290, 2020). "In non-allergic asthma, neutrophil recruitment and TNF-α can result in AHR, but AHR can also occur independently of neutrophil recruitment or TNF." (PMID 30845921, 2019). "In allergic asthma, TLR7 activated pDC produce less IL-6, IFN-α, and TNF than pDC from healthy people." (PMID 29118754, 2017). "Elevated production of TNF-α and IFN-γ by bronchoalveolar leukocytes from a series of 11 patients with allergic asthma compared with control subjects." (PMID 23043798, 2012). "The non-canonical NF-κB pathway has been shown to regulate TNF-α induced TNFR2 ILC2 signaling in allergic asthma." (PMID 36506643, 2022). "In severe neutrophilic asthma, IFN-γ and TNF-α are increased, while IL-6 is increased in non-allergic asthma compared to allergic asthma." (PMID 35887796, 2022). "In this study, we investigated the protective effects of a methanolic extract of AH branches against airway inflammation and mucus production in tumor necrosis factor (TNF)-α-stimulated NCI-H292 cells and in an ovalbumin (OVA)-challenged allergic asthma mouse model." (PMID 33643046, 2021). "A review of the evidence shows that tumor necrosis factor (TNF-α), interferons (IFN-α/INF-β) and interleukins (IL-1α/IL-1β, IL-4–IL-6, IL-10, IL-13, IL-15–IL-20, IL-25, IL-31–IL-33) play a key role in the pathogenesis of allergic asthma." (PMID 33339172, 2020). "Generally, cytokines play a central role in the pathogenesis of allergic inflammation, with related studies documenting that both pro-inflammatory cytokines and chemokines, including TNF-α, IL-6, NO, and CXCL8, contribute to the pathogenesis and exacerbation of allergic asthma." (PMID 33261109, 2020).